PGRMC1 (progesterone receptor membrane component 1)
Diseases named in the same sentence as PGRMC1 in open-access papers (continued):
Sharing a sentence is not in itself a finding about the gene and the disease.
Alzheimer disease (16 papers, 2013 to 2026). A progressive, neurodegenerative disease characterized by loss of function and death of nerve cells in several areas of the brain leading to loss of cognitive function such as memory and language. "The PGRMC1-related pathway has been found to associate with cognitive impairment in Alzheimer’s disease, but its role in psychiatric disorders needs further verification." (PMID 37816766, 2023). "PGRMC1 is a well identified hormone receptor with multiple functions in Alzheimer’s disease, α-synucleinopathies, and retinal disease." (PMID 37047224, 2023). "Progesterone receptor membrane component 1 (PGRMC1) increases the neuronal toxicity of amyloid beta-peptides by binding to the amyloid beta oligomer in Alzheimer’s disease." (PMID 36440278, 2022). "Future studies should urgently explore the relationship between PGRMC1 signaling and diseases such as cancer, diabetes, Alzheimer’s disease, and others." (PMID 32245408, 2020). "A neuropathology that involves TNFα-mediated neuroinflammation and Pgrmc1 signaling is Alzheimer’s disease (AD), a progressive neurological disease that results in cognitive impairment and memory loss." (PMID 31026287, 2019). "PGRMC1 is thought to mediate the protective effects of progesterone on rats modeling Alzheimer’s disease via inhibition of the mitochondrial apoptotic mechanism." (PMID 28362802, 2017). "In summary, considering our analysis, we suggest that future research should focus on characterizing the state of PGRMC1 phosphorylation and its involvement in important disease processes such as cancer and Alzheimer's disease." (PMID 27448967, 2016). "Progesterone receptor membrane component 1 (PGRMC1) is a multifunctional protein implicated in multiple pathologies, including cancer and Alzheimer's disease." (PMID 27448967, 2016). "Expression of sigma-2/PGRMC1 is upregulated in vitro by treatment with Abeta oligomers, and is dysregulated in Alzheimer's disease patients' brain compared to age-matched, normal individuals." (PMID 25390692, 2014). "Several lines of evidence connect S2R to Alzheimer’s disease; these include its localization to neuronal synapses, amyloid-β oligomers, and learning and memory, including data from studies genetically or pharmacologically manipulating S2R constituents and interacting proteins, including PGRMC1." (PMID 37047224, 2023). "Progesterone receptor membrane component 1 (PGRMC1) is a multifunctional heme-binding protein involved in various diseases, including cancers and Alzheimer’s disease." (PMID 29445107, 2018). "In the absence of PGRMC1, there was an increase in cytokine activity during inflammatory states, and markers related to Alzheimer’s disease also showed an elevation." (PMID 38397828, 2024). "Regardless of the precise mechanism, sigma-2/PGRMC1 selective small molecule antagonists have the potential to be disease-modifying therapeutics for Alzheimer's disease patients." (PMID 25390692, 2014). "The requirement for microglial activation in the P4-E2 antagonism of neurite outgrowth further suggests that microglial activation, such as arises during aging and Alzheimer disease, might alter the absence of P4-E2 antagonism in regulation of hippocampal neuron Pgrmc1 in vivo." (PMID 24027494, 2013).
lung carcinoma (11 papers, 2012 to 2025). "PGRMC1 is induced in a number of cancer types, including breast, ovarian and lung cancers, and a small study indicated that PGRMC1 is associated with poor survival in lung adenocarcinoma." (PMID 27867772, 2015). "Since then, a number of studies demonstrated that PGRMC1 induced drug resistance in a variety of cancers, including breast, ovarian, uterine, colon, and lung cancer." (PMID 37887342, 2023). "Most recent studies also reveal that progesterone receptor membrane component 1 (PGRMC1) is the prospective therapeutic target in lung cancer." (PMID 37193898, 2023). "Recently, PGRMC1 has been reported to interact with the insulin receptor and to regulate glucose uptake in lung cancer cells." (PMID 32887925, 2020). "The information suggests that the expression level or genomic alternation of PGRMC1 has clinical relevance in lung cancer." (PMID 32179851, 2020). "For example, measuring the level of serum PGRMC1 is useful in assessing the stage of lung cancer, particularly the stage 1 cancer where the cancer limited to the lung and hasn't spread to the lymph nodes and wherein the tumor is generally smaller." (PMID 28107520, 2017). "For example, it has indicated that the serum PGRMC1 level was significantly different in lung cancer patients with adenocarcinoma, squamous cell lung cancer and large cell lung cancer." (PMID 28107520, 2017). "We report here that PGRMC1 is abundant in lung cancer-derived stem cells from patients, and PGRMC1 inhibition triggered cell death in lung cancer stem cells where other therapeutic classes failed." (PMID 27867772, 2015). "In lung cancer cells, the prominent localization for PGRMC1 is cytoplasmic puncta, including early endosomes, and numerous groups have reported similar findings in other cell types." (PMID 27867772, 2015). "PGRMC1 is essential for lung tumor formation and metastasis, so we determined PGRMC1 levels by immunohistochemistry in 330 lung cancer samples using tissue microarrays, which included 58 patients with survival data." (PMID 27867772, 2015). "Using immunohistochemistry of paraffin-embedded tissue, we also confirm previous findings from western blots of frozen tissue that PGRMC1 staining correlated with survival in lung cancer patients." (PMID 27867772, 2015). "Notably, in the plasma of lung cancer patients, PGRMC1 expression is significantly elevated, making it a promising new therapeutic target for lung cancer." (PMID 41153737, 2025). "Previous studies have shown PGRMC1 is induced in many different types of cancers, including breast, thyroid, colon, ovary, and lung cancers, and required for the key functions of tumor growth, cancer cell survival, and motility, particularly after chemotherapeutic drugs." (PMID 31970154, 2019). "Finally, PGRMC1 is secreted by lung cancer cells, where it has a pro-proliferative function, and is detected in the plasma of lung cancer patients." (PMID 27867772, 2015). "Recently, it has been reported that PGRMC1 directly interacts with insulin receptor (IR) in lung cancer cells, but PGRMC1 knockdown did not change the phosphorylation of Akt, which is downstream of IR30." (PMID 32887925, 2020).
diabetes (10 papers, 2017 to 2025). "PGRMC1 is also implicated in various pathophysiological outcomes such as non-alcoholic fatty liver disease, diabetes and cancer, which parallel the emerging role of the TPC complex in many of the same disease states." (PMID 37866635, 2023). "We speculated that P4 is the causal factor for diabetes through the regulation of PGRMC1." (PMID 33005004, 2020). "Consistently, patients with insulin resistance (IR) or diabetes mellitus (DM) exhibited higher PGRMC1 expression in skeletal muscle compared to those with insulin sensitivity (IS)." (PMID 41208560, 2025). "One of the progesterone receptors, progesterone receptor membrane component 1 (Pgrmc1), has been reported to suppress obesity/diabetes-mediated cardiac lipotoxicity." (PMID 36899888, 2023). "While the role of progesterone (P4) in diabetes is controversial, the P4 receptor, progesterone receptor membrane component 1 (PGRMC1), is known to stimulate pancreatic insulin secretion." (PMID 33005004, 2020). "The meta-analysis results showed that the PGRMC1 were significant across diabetes studies, presenting six out of 13 studies with the U-score ≤ 0.05, and the IRS1 gene was significant in four studies of insulin response (i.e., U-score ≤ 0.05)." (PMID 28117714, 2017). "Furthermore, the regulation of cardiac health by Pgrmc1 has been investigated only in the energy-enriched state in diabetes." (PMID 36899888, 2023). "Our study suggests that PGRMC1 may be an emerging target for controlling gluconeogenesis and diabetes in an insulin-resistant state." (PMID 33005004, 2020). "For PGRMC1 and HADH, their associations ranked at the top 5% (i.e., U-score ≤ 0.05) in the six diabetes studies and their best U-scores were 0.34% and 0.44% in the diabetes studies 9 and 11 of the pancreas, respectively." (PMID 28117714, 2017). "Another metabolism-related study suggests that progesterone increases hepatic glucose production via the modulation of gluconeogenesis by progesterone receptor membrane component 1 (PGRMC1), which may exacerbate hyperglycemia in diabetes where insulin action is limited." (PMID 35860276, 2022). "A gene expression meta-analysis also revealed the existence of possible pleiotropic mechanisms manifest via common gene signatures (PGRMC1 and HADH) across different diabetes phenotypes." (PMID 35788821, 2022). "Our analysis showed that PGRMC1 and HADH genes were significant over diabetes studies, while IRS1 and MPST genes were significant over insulin response studies, and joint analysis showed that HADH and MPST genes were significant over all combined data sets." (PMID 28117714, 2017). "Collectively, our results indicate that systemic PGRMC1 inhibition by 11α‐OHP improves metabolic outcomes even in advanced stages of diabetes, without apparent toxicity or non‐muscle‐specific adverse effects, underscoring its therapeutic potential." (PMID 41208560, 2025). "Thus, PGRMC1 acts as a size-selective cargo receptor during RTN3-dependent ER-phagy, and is a potential therapeutic target for diabetes." (PMID 34645803, 2021). "Our meta-analysis showed that PGRMC1, HADH, IRS1 and MPST were the four tissue non-specific genes presenting differential expression association with the diabetes or insulin response." (PMID 28117714, 2017).
breast tumors (9 papers, 2008 to 2022). "PGRMC1 has been associated with strong membrane expression in human breast tumor tissue." (PMID 32867363, 2020). "Overall, our in vitro and in silico analysis demonstrates that PGRMC1 plays a major role in influencing the miRNome in such a way that these alterations favor breast tumor growth and progression." (PMID 34350123, 2021). "The downloaded data showed a significant increase in PGRMC1 expression in breast tumour tissues compared with normal tissues." (PMID 32704174, 2020). "Phosphatase treatment of breast tumor proteins indicated that the PGRMC1 isoforms differed in their phosphorylation status." (PMID 18922159, 2008). "A possible ex-planation might be the sample size, and the PGRMC1 phosphorylation may be involved in the clinical differences that underpin breast tumors of differing ER status." (PMID 34746100, 2021). "PGRMC1 was reported to be over-expressed in breast tumors and other cancer cell lines." (PMID 24628760, 2014). "PGRMC1 phosphorylation may be involved in the clinical differences that underpin breast tumors of differing ER status." (PMID 18922159, 2008). "To assess whether differences in distinct two-dimensional PAGE spot isoforms were due to distinctly phosphorylated species of PGRMC1, we treated proteins from primary breast tumors with SAP and quantified differences in protein isoform abundances using inverse-replicate ProteoTope." (PMID 18922159, 2008).
endometriosis (8 papers, 2019 to 2024). The growth of functional endometrial tissue in anatomic sites outside the uterine body. "Membrane-associated progesterone receptor component 1 (PGRMC1) was similarly over-expressed in proliferative endometriosis eutopic tissue versus control (EP/CP = 1.56), and under-expressed in ectopic tissue (EcS/ES = 0.61)." (PMID 30992697, 2019). "The results showed that, compared with normal endometria, the expression of AR, PGR, and PGRMC1 in eutopic endometria derived from patients with endometriosis was decreased." (PMID 36860677, 2023). "The observation of reduced PGRMC2 is in accord with those reported in a non-human primate model of endometriosis, while only humans with endometriosis appear to also exhibit reduced PGRMC1 expression." (PMID 35406659, 2022). "We found that PGRMC1 binds to PHBs at the nucleus periphery after P4 treatment, suggesting it may function as a scaffold protein for decidualization in endometriosis stromal cells." (PMID 38308254, 2024). "In the eutopic endometria of endometriosis patients, AR, progesterone receptor (PGR) and progesterone receptor membrane component 1 (PGRMC1) showed decreased expression compared with normal endometria, with log2FC<1 in both the GSE51981 and GSE120103 datasets." (PMID 36860677, 2023). "The network of the DEGs between normal endometrium and those of patients with endometriosis contained 683 nodes and 5105 edges, with AR, PGR and PGRMC1 involved in the network construction." (PMID 36860677, 2023). "Decreased expression of PGRMC1 and PGRMC2 has been reported in the eutopic endometrium of patients with endometriosis compared to the endometrium of healthy women." (PMID 35956024, 2022). "A decrease in the expression and protein content of other membrane progesterone receptors, PGRMC1 and PGRMC2, has also been reported in the eutopic endometrium of patients with endometriosis compared to women without the disease." (PMID 32733932, 2020). "Compared to controls, macaques with endometriosis exhibited no changes in the expression or localization patterns for PGR and PGRMC1, but exhibited strikingly reduced levels of PGRMC2 transcript and altered intracellular staining patterns for the PGRMC2 protein." (PMID 35406659, 2022).
colon cancer (7 papers, 2008 to 2023). "PGRMC1 overexpresses in several types of tumours than in healthy tissues, such as breast, lung, ovary and colon cancer." (PMID 32672400, 2020). "Interestingly, PGRMC1 knockdown in the human colon cancer cell line, HCT116, has reported the contrary effect since authors evidenced a decrease in proliferation and metastasis to the liver in cells lacking this protein." (PMID 33076541, 2020). "FLAG-tagged PGRMC1 ectopically expressed in human colon cancer HCT116 cells was immunoprecipitated with anti-FLAG antibody, and co-immunoprecipitated EGFR and endogenous PGRMC1 binding to FLAG-PGRMC1 were detected by Western blotting." (PMID 26988023, 2016).
hepatocellular carcinoma (7 papers, 2016 to 2024). A malignant tumor that arises from hepatocytes. "Recent studies found an association between high gene expression of PGRMC1 and poor survival of patients with hepatocellular carcinoma, triple-negative breast carcinoma, and head-neck squamous cell carcinoma." (PMID 37887342, 2023). "Most studies have, to date, focused on the expression and role of PGRMC1 in cancers other than colorectal cancer, such as ovarian, breast, endometrial, lung, and hepatocellular carcinoma." (PMID 37894441, 2023). "We also observed that treating Hep3B cells (hepatocellular carcinoma cell line) with supernatant of Pgrmc1 KD Raw264.7 cells led to down-regulation of cancer cell proliferation." (PMID 34069911, 2021). "Interestingly, recent studies in hepatocellular carcinoma showed that PGRMC1 activated the NF-kB pathway to promote the release of Interleukin-6." (PMID 37887342, 2023). "This study reveals a novel cooperative role of Pgrmc1 in supporting the EGFR-mediated development of hepatocellular carcinoma, implying that pharmacological suppression of Pgrmc1 may be a useful strategy in HCC treatment." (PMID 34069911, 2021). "Furthermore, PGRMC1 correlates with EGFR at mRNA level in patients with hepatocellular carcinoma." (PMID 37887342, 2023). "We also showed that GL and GlucoGL inhibited the interaction between PGRMC1 and EGFR in human hepatoma HuH7 cells." (PMID 34209885, 2021). "The effect of PGRMC1 on enzymatic activity was tested by siRNA-mediated downregulation of endogenous PGRMC1, and by coexpression with functional CYP plasmids in HEK293 and HepG2 hepatoma cells." (PMID 28396637, 2017). "Chemosensitivity enhancement by two different shRNAs to PGRMC1 was seen also in HCT116 cells and human hepatoma HuH7 cells." (PMID 26988023, 2016). "Here, we first analyzed two sets of clinical data and found that the levels of PGRMC1 and EGFR in hepatocellular carcinomas (HCCs) were both inversely correlated with the survival of HCC patients." (PMID 34069911, 2021). "PGRMC1 has been reported to exist in co-precipitated protein complexes with epidermal growth factor receptor (EGFR), which is considered a useful therapeutic target in hepatocellular carcinoma (HCC)." (PMID 34069911, 2021).
premature ovarian failure (7 papers, 2010 to 2024). "A study that screened 67 women with idiopathic primary ovarian failure identified a missense mutation of progesterone receptor membrane component 1 (PGRMC1)." (PMID 34193292, 2021). "We have recently shown that reduced PGRMC1 levels are associated with premature ovarian failure (POF;)." (PMID 20537145, 2010). "The PGRMC1 role in promoting ovarian cell survival has also a clinical relevance because depletion, methylation or point mutations of its promoter have been described in women with Premature Ovarian Failure (POF)." (PMID 27008165, 2016). "There are also numerous reports linking PGRMC1 to normal ovarian function, including follicle development, and is aberrant in premature ovarian failure." (PMID 27867772, 2015). "PGRMC1 expression is also altered in women with polycystic ovarian syndrome, premature ovarian failure and infertility." (PMID 23781168, 2013). "Progesterone receptor membrane component 1 (PGRMC1) plays a clinically important role in regulating ovarian function as demonstrated by the fact that PGRMC1 levels are reduced in some women with polycystic ovarian syndrome or premature ovarian failure." (PMID 23781168, 2013). "We observed a significant down-regulation of PGRMC1 in postmenopausal women and in patients with premature ovarian failure (POF) and polycystic ovary syndrome (PCOS) when compared to early follicular phase of healthy women." (PMID 20537145, 2010). "We investigated expression levels of PGRMC1 in patients with reduced fertility, i.e. premature ovarian failure (POF) and polycystic ovary syndrome (PCOS)." (PMID 20537145, 2010). "Additionally, we determined PGRMC1 levels in samples from patients with premature ovarian failure (POF) and polycystic ovary syndrome (PCOS) as well as in healthy postmenopausal women and male controls." (PMID 20537145, 2010). "Also, the effect on CYP activity of identified PGRMC1 variants, such as the His165Arg mutant associated with premature ovarian failure, was not assessed for consequences regarding xenobiotic metabolism." (PMID 38804287, 2024). "We next analyzed PGRMC1 levels in blood samples obtained from 6 patients with polycystic ovary syndrome (PCOS) and 8 patients with premature ovarian failure (POF)." (PMID 20537145, 2010).
triple-negative breast carcinoma (6 papers, 2020 to 2023). An invasive breast carcinoma which is negative for expression of estrogen receptor (ER), progesterone receptor (PR), and human epidermal growth factor receptor 2 (HER2). "Differential PGRMC1 phosphorylation status may therefore be associated with the altered prognosis of triple negative breast cancers." (PMID 32293262, 2020). "Increased expression of the progesterone receptor membrane component 1, a heme and progesterone binding protein, is frequently found in triple negative breast cancer tissue." (PMID 34350123, 2021). "The mRNA expression of PGRMC1 in triple negative breast cancer group was significantly higher than that of LumA, LumB and the compared adjacent tissue." (PMID 34746100, 2021).